INS (insulin)
Diseases named in the same sentence as INS in open-access papers (continued):
Sharing a sentence is not in itself a finding about the gene and the disease.
type 1 diabetes (continued). "Type-1 diabetes mellitus (T1DM) is an autoimmune disorder leading to the irreversible destruction of insulin-producing cells in pancreatic islets." (PMID 30936922, 2019). "Subsequently, several studies were conducted to assess the effects of sotagliflozin added to insulin therapy in subjects with type 1 diabetes." (PMID 30819210, 2019). "In order to create an application prototype, a detailed analysis of the lifestyles and decision-making strategies of patients with type 1 diabetes regarding prandial insulin dose was provided." (PMID 31126048, 2019). "Experimental results suggest that the production of ucOC is regulated by exogenous insulin injection in patients with type 1 diabetes whose endogenous insulin secretion has been depleted." (PMID 31050684, 2019). "In parallel with histological observations, it is now clear that endogenous insulin, as measured by serum C-peptide, persists years after diagnosis in many people with type 1 diabetes." (PMID 30767048, 2019). "Type 1 diabetes (T1D) is characterized by the immune-mediated destruction of insulin-producing islet β cells." (PMID 31775218, 2019). "Of all those progressing to insulin within 3 years of diagnosis, 47% (123/264) met the study criteria for type 1 diabetes and 18% (48/264) had intermediate C-peptide (≥200–<600 pmol/l)." (PMID 30969375, 2019). "Type 1 diabetes (T1D) is an autoimmune disease in which the pancreas loses the capability of producing insulin, the hormone stimulating the absorption of blood glucose (BG) by the body tissues." (PMID 31816886, 2019). "Of all cases of diabetes, around 5–10% are of Type 1 diabetes (T1D), an autoimmune disease in which the pancreatic beta cells are destroyed and there is an insufficient level of insulin." (PMID 31168341, 2019). "Clinical trials have suggested that insulin therapy, the golden-standard treatment of conventional type 1 diabetes, also clearly applicable to the LADA patients." (PMID 31383887, 2019). "Previous studies have reported that allantoin decreased plasma glucose and improved insulin sensitivity in type 1 diabetic rats." (PMID 32373294, 2019). "Type 1 diabetes (T1D) is an autoimmune disease characterized by insufficient production of insulin resulting from the destruction of the insulin-producing β-cells of the islets of Langerhans of the pancreas." (PMID 30781593, 2019). "The effect of first generation long-acting insulin analogues in reducing nocturnal hypoglycaemia is well documented in patient with type 1 diabetes." (PMID 31337371, 2019). "This showed that 89% of those with genetically defined type 1 diabetes occurring after age 30 required insulin within a year, strikingly similar to the 85% we report using a C-peptide-based definition." (PMID 30969375, 2019). "It is not unreasonable however, to take steps to reduce blood sugar (e.g. giving an additional insulin injection if they have Type 1 diabetes) on the day of surgery if patients present with very high levels." (PMID 31086435, 2019). "The incidence of type 1 diabetes also continues to increase, and insulin remains an essential therapy in nearly all cases." (PMID 30357355, 2019). "Type 1 diabetes is an autoimmune disease that arises as a consequence of the destruction of insulin-producing pancreatic beta cells by the immune system." (PMID 31444528, 2019). "Type 1-diabetes (T1D) is a chronic autoimmune disease diagnosed commonly during early childhood and is characterized by immune-mediated destruction of the insulin-producing pancreatic beta (β)-cells." (PMID 30832381, 2019). "Hypoglycaemia is the main side-effect of insulin therapy in type 1 diabetes and remains a major source of daily concern for patients and their relatives." (PMID 31337371, 2019). "Type 1 diabetes is often characterized by rapid autoimmune damage of pancreas islet β cells, which further results in insulin treatment dependency of the patient." (PMID 31383887, 2019).
type 1 diabetes (continued). "This also happened to some of our informants with type 1 diabetes, if their insulin metabolism was regular enough." (PMID 31599983, 2019). "Physically active adults with type 1 diabetes have better blood pressure, a healthier BMI, lower requirements for insulin and less ketoacidosis than their physically inactive counter-parts." (PMID 31161377, 2019). "Type 1 diabetes (T1D) is a chronic autoimmune disease leading to immune-mediated destruction of pancreatic beta cells, resulting in the need for insulin therapy." (PMID 31514368, 2019). "Type 1 diabetes consequences of the autoimmune destruction of the pancreas's beta cells, which produce insulin." (PMID 31663031, 2019). "The importance of regular exercise for glucose management in individuals with type 1 diabetes is magnified by its acknowledgment as a key adjunct to insulin therapy by several governmental, charitable, and healthcare organisations." (PMID 31428047, 2019). "A clinical implication of this is that within one or two days after delivery, restoration of insulin requirements towards prepregnancy levels, or even lower, is seen in mothers with type 1 diabetes." (PMID 31828161, 2019). "Clinical studies showed that administration of camel milk as adjunct therapy with insulin to patients of type 1 diabetes reduced insulin requirement by up to 30%." (PMID 30838017, 2019). "The mean duration of insulin administration until the onset of type 1 diabetes was 7.7 ± 6.1 months." (PMID 30970177, 2019). "Insulin formulations are used to treat type 1 diabetic patients through multiple-daily subcutaneous injections (MDSIs) or continuous subcutaneous insulin infusion (CSII)." (PMID 31687164, 2019). "Patients with type 1 diabetes should have certain skills and attitudes, such as being aware of insulin types and treatment options; correct injection techniques; and the importance of giving the right dose at the right time." (PMID 30905141, 2019). "Type 1 diabetes requires insulin injections, whereas type 2 is managed with diet, exercise, tablets or insulin injections, if needed." (PMID 31086435, 2019). "Using highly sensitive C‐peptide assays up to 80% of those with long duration Type 1 diabetes (median duration 18 years) have been shown to have low‐level, detectable endogenous insulin secretion." (PMID 30955221, 2019). "In the flexible meal dosing group, the algorithm used to treat type 1 diabetes with insulin pumps was adopted." (PMID 30871141, 2019). "Type 1 diabetes (T1D) is an autoimmune disease characterized by a T-cell-mediated destruction of insulin-producing β-cells in the pancreas." (PMID 30723474, 2019). "As such, elevated levels of methylated and/or unmethylated INS DNA in people with new-onset type 1 diabetes have been reported." (PMID 31428654, 2019). "This study evaluated the annual costs of insulin degludec (degludec) versus insulin detemir (IDet) in children and adolescents with type 1 diabetes (T1D) in the UK." (PMID 31543973, 2019). "We have successfully developed a phenylboronic acid-functionalized gold nanocluster system (AuNC-PBA-Ins) for responsive insulin release and glucose control in type 1 diabetes." (PMID 31159842, 2019). "Type 1 diabetes (T1D) is an autoimmune disease that results in the destruction of insulin-producing islet cells in the endocrine pancreas." (PMID 31466263, 2019). "Like other major autoantigens in type 1 diabetes, ZnT8 has high beta cell specificity and is localised to insulin secretory granules." (PMID 31444530, 2019). "Type 1 diabetes is a long‐term condition requiring plenty of self‐care activities: monitoring blood glucose levels and administering insulin, diet and exercise." (PMID 30918702, 2019). "They found that the insulin sensitivity was around 30% less than the nominal values, showing that the insulin sensitivity of the S2013 simulator should be further modified to represent people with type 1 diabetes." (PMID 31344037, 2019).
type 1 diabetes (continued). "Several studies have reported that high GADA‐RIA titers (≥10 U/mL) are associated with the progression of β‐cell failure and are also predictive of future insulin requirements in slowly progressive type 1 diabetes patients." (PMID 30919585, 2019). "There is significant interest in automated insulin delivery systems for caregivers of children with type 1 diabetes." (PMID 31140654, 2019). "Fully functional pancreatic β‐cells derived from hES cells would effectively replace exogenous insulin treatment as a renewable source of cellular therapy, greatly enhancing the quality of life for countless individuals affected by type 1 diabetes." (PMID 30521112, 2019). "In people with type 1 diabetes, prandial insulin doses are individualized using parameters such as the insulin-to-carbohydrates ratio, and much less frequently, the circadian fluctuations of this parameter." (PMID 30871141, 2019). "Type 1 diabetes (T1D) is a T cell mediated autoimmune disease resulting from the destruction of insulin-producing pancreatic β-cells." (PMID 31798584, 2019). "Individuals with Type I diabetes are unable to produce insulin themselves and thus are treated with exogenous injections of insulin on an almost daily basis." (PMID 31367382, 2019). "Regarding the influence on type 1 diabetes, the required daily dose of insulin and hemoglobin A1c (HbA1c) levels decreased." (PMID 31360575, 2019). "Animal studies have shown anti-insulin B cells are important in the pathogenesis of type 1 diabetes." (PMID 31444529, 2019). "While some complained about metformin for T2DM, others were more concerned about insulin, which is mostly used in type 1 diabetes." (PMID 31619234, 2019). "Recent work has shown that many individuals with long duration Type 1 diabetes continue to produce low levels of endogenous insulin; however, the clinical significance of this is uncertain." (PMID 30955221, 2019). "Very recently, it was shown that deletion of senescent beta cells in a mouse model of type 1 diabetes enhanced insulin secretion and preserved insulin secretory capacity, providing a novel link between cellular senescence and severe insulin deficiency." (PMID 31451866, 2019). "Parents/caregivers of 20 children aged 1 to 7 years with type 1 diabetes completed a closed‐loop experience survey following two 3‐week periods of unrestricted day‐and‐night hybrid closed‐loop insulin therapy using Cambridge FlorenceM system at home." (PMID 31140654, 2019). "The key to efficiently treat type 1 diabetes is to accurately inject insulin according to the blood glucose levels." (PMID 31159842, 2019). "Glucose responsive systems that release insulin automatically in a way that mimics physiological insulin secretion provide a better way and have the potential to change the way in which type 1 diabetes is managed." (PMID 31119124, 2019). "In type 1 diabetes, it is generally accepted and considered to be beneficial to take into account the carbohydrate content of the meals when adjusting the prandial insulin doses." (PMID 30871141, 2019). "Type I diabetes is an autoimmune diseases, in which insulin-producing pancreatic cells are destroyed by activated T lymphoctyes." (PMID 31781097, 2019). "Patients, especially with type 1 diabetes, can be made insulin independent for over 5 years through transplantation of new β cells." (PMID 31547878, 2019). "Previous studies have reported that that OA possesses synergistic pharmacological effects with insulin in STZ-induced type 1 diabetic rats as they were found to have anti-hyperglyaecemic, antiglycation, antioxidant and hepatoprotective properties." (PMID 29596390, 2018). "Type 1 diabetes (T1D) arises following the autoimmune destruction of insulin-producing pancreatic β cells." (PMID 29541642, 2018). "Increases in BMI and related BP in individuals with type 1 diabetes have been well documented as long-term consequences of intensified insulin treatment." (PMID 29101422, 2018).
type 1 diabetes (continued). "Twenty IU-insulin-loaded TMAP maintained the type 1 diabetic rats in a normoglycemic state for approximately 11.63 h, the longest therapeutic duration among all previously reported results on microneedle-based transdermal patches." (PMID 30182757, 2018). "By contrast, other studies have reported lower insulin requirement for the control of type 1 diabetes in patients receiving SSRIs." (PMID 29693021, 2018). "There were six statistically overrepresented pathways involved in glucose metabolism, including glucagon signaling pathway, insulin secretion, glycolysis/gluconeogenesis, aldosterone synthesis and secretion, type I diabetes mellitus, and propanoate metabolism." (PMID 30233306, 2018). "Type I diabetes is cellular-mediated auto-immune destruction of the insulin producing β-cells of the pancreas resulting in life-long dependence on exogenous insulin." (PMID 29621153, 2018). "At present, the daily exogenous insulin replacement for the lifetime is the only available therapeutic option to manage majority of patients with type 1 diabetes mellitus (T1DM)." (PMID 30425682, 2018). "C-peptide measurement after a standard meal (stimulated C-peptide) is the primary way to evaluate insulin secretion in type 1 diabetes." (PMID 29404672, 2018). "For now, sensor-integrated insulin delivery has shown promise as a tool in the management of type 1 diabetes in pregnancy." (PMID 29383544, 2018). "The introduction of intensified insulin therapy for patients with type 1 diabetes mellitus (T1D) has led to decreased prevalence of diabetic retinopathy, nephropathy and neuropathy." (PMID 29785272, 2018). "Type 1 diabetes (T1D) is a T-cell mediated autoimmune disease where T-cells are directed against pancreatic insulin-producing beta-cells." (PMID 30211164, 2018). "Currently, insulin treatment strategies in type 1 diabetes include either multiple daily insulin injections or continuous subcutaneous insulin infusion with an insulin pump." (PMID 29669716, 2018). "Nociceptive pain behaviour was investigated in a chemically induced model of type 1 diabetes (streptozotocin induced, insulin supplemented; either vehicle or VEGF‐A165b treated) and an inducible endothelial knockdown of VEGFR2 (tamoxifen induced)." (PMID 29774557, 2018). "Insulin therapy is also a major confounder in all studies attempting to examine the effect of a lifestyle intervention on HbA1c in type 1 diabetes." (PMID 29596460, 2018). "In the experimental model of type 1 diabetes employed in this study, the insulin producing cells in pancreas are destroyed by streptozotocin that is injected into the peritoneal cavity." (PMID 30242286, 2018). "Basal insulin (BI) infusion in pump therapy of type 1 diabetes (T1DM) mimics physiological secretion during the night and between meals." (PMID 29974056, 2018). "All participants had type 1 diabetes and were either on multiple daily injections (30%) or continuous subcutaneous insulin infusion (70%)." (PMID 30067410, 2018). "The current study aimed at investigating the molecular mechanism(s) through which RA-3 improves insulin signaling in streptozotocin-induced type 1 diabetic rats." (PMID 30285704, 2018). "Replacement of destructed β-cells by transplanting islets from human cadaveric pancreata achieves euglycemia and insulin independence in subsets of patients with type 1 diabetes." (PMID 28916910, 2018). "Management of type one diabetes mellitus (T1DM) which sometimes is referred to as children type or insulin-dependent diabetes necessitates multiple daily insulin injections and pinpricks for measurement of blood glucose levels." (PMID 29373983, 2018). "Intriguingly, TNFR2 agonism effectively and selectively induces the apoptosis of insulin-autoreactive CD8+ cells in patients with type 1 diabetes." (PMID 29619032, 2018).
type 1 diabetes (continued). "Women with type 1 diabetes, type 2 diabetes or gestational diabetes requiring insulin were randomised to intermittent masked CGM for 5–7 days every 6 weeks vs. standard of care." (PMID 29383544, 2018). "FMD cycles restore insulin secretion and glucose homeostasis in both type 2 and type 1 diabetes mouse models." (PMID 29480368, 2018). "We generated Tlr9−/− NOD mice and examined them for type 1 diabetes development and beta cell function, including insulin secretion and glucose tolerance." (PMID 30094467, 2018). "In conclusion, rotation of injections over the large area and use of rapid plus long-acting insulin analogs in patients with type 1 diabetes are the foremost and modifiable factors for minimizing insulin-related lipohypertrophy." (PMID 30425682, 2018). "Although insulin pumps were first available in the 1980s, they are currently used by about 50% of individuals with type 1 diabetes in the US and by only about 1 million users globally." (PMID 29682315, 2018). "Type 1 diabetes care requires i) insulin treatment, food intake and life style to be handled in concert, ii) this need cannot be replaced by arbitrary addition of add-on GLDs, and iii) training to this end is 75% cheaper at a DRC than in standard hospitals." (PMID 29529063, 2018). "We assessed the effectiveness of day-and-night hybrid closed-loop insulin delivery compared with sensor-augmented pump therapy in people with suboptimally controlled type 1 diabetes aged 6 years and older." (PMID 30292578, 2018). "In type 1 diabetes, blood glucose excursions are a function of the input of glucose from food, mainly carbohydrates (starch and sugars), and insulin from predominantly exogenous sources." (PMID 29596460, 2018). "Protection of beta cells from apoptosis led to blood insulin‐level promotion and decreasing of blood glucose level in type 1 diabetes." (PMID 30510749, 2018). "Non-insulin adjunct therapies in type 1 diabetes have been proposed as a means of improving glycaemic control and reducing risk of hypoglycaemia." (PMID 30132030, 2018). "The main objective of the present study is to examine the impact of overestimating a meal insulin bolus (erroneous categorization) in the context of dual-hormone closed-loop delivery with a simplified meal bolus strategy in adult patients with type 1 diabetes." (PMID 29422651, 2018). "In the subgroup analyses, the results indicated that children with type 1 diabetes needed significantly less daily insulin doses after 12 months of CSII treatment as compared with MDI (WMD=-0.21, 95% CI=-0.36 to -0.05, p=0.009)." (PMID 30015622, 2018). "In type I diabetes, pancreatic ß-cells that are responsible for insulin production are functionally compromised due to auto-immunological disorders, giving rise to hyperglycemia." (PMID 29713373, 2018). "Type 1 diabetes (T1D) results from the autoimmune destruction of insulin-producing beta cells in the pancreatic islets of Langerhans, culminating in the loss of blood-glucose homeostasis." (PMID 30213104, 2018). "Type 1 diabetes (T1D) is an autoimmune disease characterized by insufficient insulin production as a result of T-cell-mediated destruction of insulin-secreting pancreatic beta cells." (PMID 29584630, 2018). "Type 1 diabetes develops when pancreatic beta cells fail to produce sufficient insulin to maintain euglycaemia." (PMID 29404672, 2018). "All participants had type 1 diabetes with either continuous subcutaneous insulin infusion (70%) or multiple daily injections (30%) as their therapy regimen." (PMID 30067409, 2018). "Its effect on peripheral insulin signaling in skeletal muscle of STZ-induced type 1 diabetic rats was investigated in this study." (PMID 30285704, 2018). "Oral glucose-lowering efficacy of ExpressTec-ProINS-Tf and insulin was also investigated in the STZ-induced type 1 diabetic mouse model in comparison to the subcutaneously injected proteins." (PMID 29373562, 2018).